BTG2 (BTG anti-proliferation factor 2)
Diseases named in the same sentence as BTG2 in open-access papers (continued):
Sharing a sentence is not in itself a finding about the gene and the disease.
ovarian carcinoma (1 paper, 2021). A malignant neoplasm originating from the surface ovarian epithelium. "Our data revealed that lower expression of BTG2 in ovarian cancer patients was associated with tumor progression and shortened survival." (PMID 34485119, 2021). "Ovarian cancer exhibits a high mutational load compared to other tumor types, and top 5 most frequently mutated genes included BTG2." (PMID 34485119, 2021). "BTG2 was significantly associated with ovarian cancer FIGO stage and grade in the clinic." (PMID 34485119, 2021). "Thus, BTG2 was downregulated in ovarian cancer tissues and associated with patient survival." (PMID 34485119, 2021). "BTG2 inhibited ovarian cancer cell proliferation and migration, induced cell cycle arrest and enhanced cisplatin sensitivity in vitro." (PMID 34485119, 2021). "A tissue cohort composed of tumor and adjacent normal tissues from 38 ovarian cancer patients was employed to address the expression alteration and clinical implications of BTG2." (PMID 34485119, 2021). "We found that the proliferation of ovarian cancer cells was inhibited by BTG2 and confirmed the effects and mechanisms of BTG2-sensitized ovarian cancer by establishing nude mouse xenograft models using the BTG2 shRNA- and NC-transfected A2780 cells." (PMID 34485119, 2021). "To further investigate the effect of BTG2 expression on ovarian cancer progression, we overexpressed and knocked down BTG2 in ovarian cancer cell lines." (PMID 34485119, 2021). "BTG2 inhibited ovarian cancer cell proliferation and migration, blocked the ovarian cancer cell cycle and enhanced the cisplatin sensitivity of ovarian cancer cells." (PMID 34485119, 2021). "Our results showed that BTG2 expression regulated ovarian cancer cell proliferation via G1/S phase cell cycle arrest by regulating Cyclin D1, CDK4, p-AKT, and p-ERK expression." (PMID 34485119, 2021). "The flow cytometry results indicated that BTG2 could induce G1 cell cycle arrest in ovarian cancer cells." (PMID 34485119, 2021). "We further explored whether dysregulation of BTG2 inhibited ovarian cancer growth by modulating the cell cycle." (PMID 34485119, 2021). "The results above indicated that BTG2 arrested cells in G1 phase, which may contribute to inhibiting ovarian cancer growth." (PMID 34485119, 2021). "Furthermore, xenograft models confirmed a growth inhibitory effect of BTG2 in ovarian cancer in vivo." (PMID 34485119, 2021). "Our findings indicated that BTG2 exerts a suppressive impact on ovarian cancer and could be a potential biomarker." (PMID 34485119, 2021). "PPI networks in ovarian cancer were constructed to identify the BTG2 gene." (PMID 34485119, 2021). "This study indicated that BTG2 may be a tumor suppressor and a potential biomarker for ovarian cancer patients." (PMID 34485119, 2021). "Indeed, lower expression of BTG2 increased cell migration in ovarian cancer cells." (PMID 34485119, 2021). "This study found that BTG2 could increase the sensitivity of ovarian cancer cells to cisplatin." (PMID 34485119, 2021). "This study showed that BTG2 expression decreased with tumor grade and FIGO stage in ovarian cancer patients." (PMID 34485119, 2021). "The results of this study also indicated that BTG2 suppressed the phosphorylation of AKT and ERK, which may result in inhibiting ovarian cancer growth." (PMID 34485119, 2021).
ovarian tumor (1 paper, 2021). "BTG2 protein expression in ovarian tumor tissue samples (n=30) was significantly lower than that in normal ovarian tissue samples (n=8) (p<0.05)." (PMID 34485119, 2021). "Furthermore, knockdown of BTG2 expression contributed to ovarian tumor formation in a mouse xenograft assay." (PMID 34485119, 2021).
pancreatic adenocarcinoma (1 paper, 2023). "In the pancreatic adenocarcinoma TCGA data, BTG2 expression is significantly suppressed in tumor tissues compared to normal tissues." (PMID 36765032, 2023).
progeria (1 paper, 2023). "Consistent with previous results, Btg2, p21, IL6, Mmp12, and Atl3 were significantly downregulated by the dCas9‐Oct4 activator in these tissues of progeria mice." (PMID 36964992, 2023).
systemic lupus erythematosus (1 paper, 2023). An autoimmune multi-organ disease typically associated with vasculopathy and autoantibody production. "Olfactory conduction, Systemic lupus erythematosus were active when BTG2 was active at low BTG2 expression." (PMID 37006240, 2023). "At this time, the active biological function of BTG2 was Olfactory conduction, Systemic lupus erythematosus." (PMID 37006240, 2023). "BTG2 was low expression in LUAD and systemic lupus erythematosus." (PMID 37006240, 2023).
tumor (163 papers, 2010 to 2026). "Previous experimental studies have demonstrated that a deficiency of BTG2 in mast cells promotes an immunosuppressive state within the tumor microenvironment (TME) and contributes to chemotherapy resistance." (PMID 40313959, 2025). "BTG2 has been found to be associated with modulating tumor cytological behavior and regulating cell differentiation in previous studies." (PMID 38494504, 2024). "And low expression of BTG2 is associated with high tumor recurrence rate and low overall survival rate." (PMID 36591524, 2022). "CCL20, MMP14, and PCDH7 were upregulated in LUAD tumor tissues and linked to poor clinical outcomes, while BTG2, CD69, GPC3, IL7R, and NMUR1 are the opposite." (PMID 34881236, 2021). "BTG2 is a tumour suppressor gene, and the protein encoded by this gene is a member of the BTG/Tob family." (PMID 34187411, 2021). "Basically, BTG2 is an early response gene associated with cell cycle, DNA damage and tumor cell apoptosis." (PMID 34699325, 2021). "Among the genes consistently altered in HT29, HCT116, and SW620 cells, 13 genes had previously been reported associated with tumor metastasis, such as BTG2, MXD1, CDKN1A, and HMGA2." (PMID 33791222, 2021). "Hsa‐miR‐25‐3p promotes tumor cell proliferation by targeting tumor suppressor BTG2; this miRNA is a new diagnostic and therapeutic target in triple‐negative BC28; however, its potential to be a reliable biomarker in BC is still unclear." (PMID 34528314, 2021). "In fact, we found that in a mouse model of spontaneous MB, PC3TIS21/BTG2 deletion causes a great increase of tumor frequency due to a deficit of GCP migration." (PMID 32231994, 2020). "Low BTG2 expression was linked to high tumor grade, size, and recurrence in estrogen receptor-positive breast cancer." (PMID 31223310, 2019). "Three CpG probes (cg01798157, cg06373167, cg23371584) that detected BTG2 hypermethylation in tumour tissues were associated with lower overall survival." (PMID 29656435, 2018). "MiR-32 upregulation is associated with downregulation of the protein BTG2, and reduced BTG2 staining in radical prostatectomy specimens has been shown to predict tumour progression." (PMID 25496077, 2014). "Similarly, in the E0771 tumor-bearing mouse model, the application of IL-2 neutralizing antibodies reduced the increase in Tregs induced by BTG2 knockout and mitigated the CTL functional inhibition caused by BTG2 deficiency." (PMID 40313959, 2025). "Among them, BTG2 caught our attention, as it has been demonstrated to be an estrogen/ERα down-regulated tumor suppressor significantly associated with low survival rate in luminal-like BC, and proposed as possible molecular target for the treatment of these tumors." (PMID 39922814, 2025). "Abnormal BTG2 expression has been implicated in tumor development and progression." (PMID 31223310, 2019). "B-cell translocation gene 2 (BTG2) is a member of the antiproliferative gene family and is involved in regulating the cell cycle and apoptosis while also exerting tumor-suppressive functions." (PMID 40535133, 2025). "Using flow cytometry and immunofluorescence staining, we confirmed significantly lower BTG2 expression in both tumor tissues and TLN tissues in the NAC-resistant group." (PMID 40313959, 2025). "Extensive evidence supports BTG2’s tumor suppressor function via downregulation of SLC7A11 (a critical ferroptosis mediator) thereby modulating cellular susceptibility to oxidative stress." (PMID 41188368, 2025). "There are currently no published articles reporting on the regulatory effect of NOX2 on BTG2 and the correlation of their expression in tumor tissues." (PMID 41441930, 2025).
tumor (continued). "Building on these observations, we performed in vivo experiments involving tail vein injections of exogenous CFSE-labeled mast cells to verify with low BTG2 expression exhibited stronger migratory ability toward tumor sites and their draining lymph nodes." (PMID 40313959, 2025). "Mast cells with low BTG2 expression were identified in the metastatic lymph nodes and in situ tumor of the NAC-resistant group." (PMID 40313959, 2025). "On the other hand, low-BTG2-expressing mast cells stimulate fibroblasts to secrete collagen, forming a rigid tumor niche that impedes the penetration of chemotherapeutic drugs, further exacerbating resistance to treatment." (PMID 40313959, 2025). "Studies on ESCC have shown that BTG2 expression in tumor tissues is significantly lower than in adjacent normal tissues and is strongly associated with postoperative metastasis, lymph node metastasis, and clinical stage of patients." (PMID 41441930, 2025). "Mast cells with BTG2 knockdown or overexpression were injected into E0771 tumor-bearing mice undergoing doxorubicin (ADM) treatment." (PMID 40313959, 2025). "In the M6A-dependent pathway, VIRMA regulates key oncogenes (e.g., FOXM1, HK2) and tumor suppressor genes (e.g., RND3, BTG2), affecting the proliferation, metastasis, metabolic reprogramming, and drug resistance of tumor cells." (PMID 40723784, 2025). "Previous studies have shown that BTG2 inhibits tumor migration ability by regulating the production of mitochondrial reactive oxygen species (ROS)." (PMID 40313959, 2025). "Mechanistically, the mast cells with low BTG2 suppress anti-tumor immunity by inducing Treg cell production through IL-2 secretion, particularly within tumor-draining lymph nodes." (PMID 40313959, 2025). "There is substantial evidence that BTG2, a well-characterized tumor suppressor gene, plays a critical role in suppressing the migratory capacity of tumor cells by modulating key molecular pathways that govern cell movement and invasion." (PMID 40313959, 2025). "The expression of NOX2 in tumor tissues was significantly higher than that in adjacent tissues, whereas BTG2 expression in tumor tissues was significantly lower than that in adjacent tissues." (PMID 41441930, 2025). "Among the genes commonly occupied by ERα and EZH2, the tumor suppressor BTG2 was selected for validation, based on its crucial role as cancer antagonist." (PMID 39922814, 2025). "Some studies have identified an important role for the BTG1 and BTG2 genes in tumor suppression, i.e., a decreased expression of these genes results in more severe malignant neoplasms, leading to death." (PMID 38357499, 2024). "The correlation of BTG2 with immune reactions was confirmed by a group of scientists, who proved that the expression of this gene is significantly correlated with tumor purity." (PMID 38357499, 2024). "From the results of this study, when BTG2 was low expression and SerpinB5 was high expression, the macrophage infiltration level in tumor tissue increases, and the prognosis was poor." (PMID 37006240, 2023). "BTG2 was considered to be a tumor suppressor, which was highly expressed in a variety of normal tissues." (PMID 37006240, 2023). "Among the candidate lists of target genes, we focused on the Btg2 gene, which has been studied as a tumor suppressor whose expression is suppressed in several types of cancer." (PMID 36765032, 2023). "Twenty genes that were commonly upregulated by NTX-301 in the three different CCLs were involved in immune activation, and these genes included known tumor suppressors such as BTG2, ALOX5, SOCS1, and TP53INP1." (PMID 36980623, 2023). "In the process of tumor occurrence and development, BTG2 played an important role in cell proliferation, differentiation, apoptosis and DNA damage repair." (PMID 37006240, 2023). "As a result, BTG1 and BTG2 are considered as tumor suppressors and closely correlated with tumor cell behavior as well as prognosis." (PMID 38062199, 2023).
tumor (continued). "NKX2–2AS modulates SHH-induced MB formation in vitro by functioning as miRNA sponge for miR-103 and miR-107, thereby de-repressing their tumor suppressive targets BTG2 and LATS1 and limiting tumor cell proliferation and migration." (PMID 36923440, 2023). "The expression of BTG2 mRNA in the model group was lower than that in the blank group, and BA can up-regulate the level of BTG2 mRNA in tumor tissues, compared with the model group." (PMID 37415745, 2023). "Expressions of Btg2 and Dll4, previously studied as tumor suppressors, were upregulated in the Vactosertib and T1-44 combination treatment group." (PMID 36765032, 2023). "GBM-derived EVs contain miR-21 which downregulates the target tumor-suppressive gene Btg2 (B cell translocation gene 2) in microglial cells." (PMID 36361947, 2022). "B‐cell translocation gene 2 (BTG2) is involved in numerous important biological processes in cancer cells acting as a tumor suppressor." (PMID 35587712, 2022). "What’s more, the inhibitory effects of RBP-J OE Mφ-Exos on the tumor growth in vivo were eliminated when circRNA BTG2 was knocked down in Mφ." (PMID 35643814, 2022). "The TGA database assessment of the TCGA database for LUAD patients revealed that individuals with elevated levels of endogenous BTG2 expression (in tumor tissues) tend to have better clinical outcomes." (PMID 36157236, 2022). "The most frequently mutated genes in the tumor tissue cohort were DTX1 (37%), CD79B (35%), BTG1 (30%), BTG2 (30%), and TMSB4X (30%)." (PMID 36280874, 2022). "First, we found that the expression of BTG2 was repressed in RCC tumour tissues compared to normal tissues based on TCGA database." (PMID 36591524, 2022). "In accordance with the pathway analysis, literature data report that the principal targets of hsa-miR-25-3p are two tumor suppressor genes involved in the proliferation, apoptosis, and DNA repair (BTG2), and in the PI3K/AKT pathway (PTEN)." (PMID 36553635, 2022). "Studies have shown that overexpression of BTG2 can repress in vitro cellular growth and BTG2 serves as a tumor suppressor gene in various types of malignant tumors." (PMID 36157236, 2022). "The results showed significant downregulation of BTG2 in tumor tissues compared to adjacent normal tissues." (PMID 36591524, 2022). "Taken together, our data show that BTG2 functions as a tumor suppressor and is frequently silenced via m6A modification in RCC." (PMID 36591524, 2022). "BTG2 is recognized as a tumor suppressor, and its overexpression has been revealed to suppress LC cell proliferation." (PMID 36497225, 2022). "Our study also showed a significant difference in the expression level of BTG2 gene in normal renal tissues and tumor tissues." (PMID 36591524, 2022). "Specifically, NKX2–2-AS1 functions as a miRNA sponge to sequester miR-103, miR-107 and miR-548m, thereby maintaining the expression of their tumor-suppressive targets BTG2 (BTG anti-proliferation factor 2), LATS1 (large tumor suppressor kinase 1) and LATS2." (PMID 34316694, 2021). "Nkx2-2as functions as a ceRNA to sequester miR-103/107 and miR-548 m, and it downregulated the tumor suppressors BTG2/Tis21/PC3 and LATS1/2, promoting tumor growth both in vitro and in vivo." (PMID 34552822, 2021). "To investigate the effects of BTG2 expression on tumor growth in vivo, we subcutaneously injected BTG2 shRNA and normal control A2780 cells into the posterior ventral side of nude mice." (PMID 34485119, 2021). "BTG2 is a recently recognized tumor suppressor belonging to the TOB/BTG family, and a study shows that BTG2 expression is reduced in NSCLC tissues and is linked to shorter OS for patients." (PMID 34881236, 2021). "The tumor suppressor BTG2 served as a regulator of myocardial necrosis by inhibiting AKT/ERK while activating glycogen synthase kinase 3 (GSK3) and cyclophilic protein D." (PMID 34217312, 2021).